SFRP5 (secreted frizzled related protein 5)
Diseases named in the same sentence as SFRP5 in open-access papers (continued):
Sharing a sentence is not in itself a finding about the gene and the disease.
breast carcinoma (18 papers, 2008 to 2023). "SFRP5 is underexpressed in moderate tumor tissues including lung cancer, ovarian cancer, GC, and breast cancer tissues, and is associated with poor prognosis." (PMID 36618366, 2022). "The epigenetic inactivation of secreted SFRP5 gene, especially SFRP5 promoter hypermethylation was associated with poor prognosis in breast cancer." (PMID 35701840, 2022). "Although over twenty adipokines are known; only twelve (adiponectin, leptin, IL-6, TNF-α, HGF, PAI–1, resistin, secreted frizzled-related protein 5 (SFRP-5), lipocalin 2, IL-8, apelin and visfatin) have been implicated in breast cancer." (PMID 29088874, 2017). "Previous studies has identified association of SFRP5 promoter hypermethylation with Acute myeloid leukemia, ovarian cancer, gastric cancer, oral squamous cell carcinoma, pancreatic cancer and breast cancer." (PMID 23009178, 2012). "Afterward, the high level of SFRP5 in plasma and tumor tissue was related to better clinical factors in breast cancer patients, such as BMI and LN metastasis, TNM stage, as well as low high Ki67 expression." (PMID 35701840, 2022). "SFRP5 inhibited EMT pathways in the breast cancer cell lines, thereby suppressing the invasive potential and, therefore, breast cancer progression." (PMID 34944905, 2021). "The adipokines plasminogen activator inhibitor 1 (PAI-1), FABP4, and secreted frizzled-related protein 5 (SFRP5) are also found in the local environment of the breast and have been shown to contribute to breast cancer progression." (PMID 34944905, 2021). "Two other members of the SFRP family, SFRP3 and SFRP5, showed substantial increase (8.6‐ to 26.1‐fold, P < 10−3) in their mRNA levels in breast cancer cells compared with normal HMECs." (PMID 33462997, 2021). "On the basis of the defined criteria, SFRP5 methylation (8.25%) was too infrequent in breast cancer sera, and thus excluded from further specificity analyses." (PMID 23320751, 2013). "For example, methylation of the Wnt antagonists SFRP5 and SFRP1 in breast cancer is an independent risk factor for adverse patients survival." (PMID 20830311, 2010). "One recent study reported that cyclinD1 and c-myc, both known as Wnt targer genes, were significantly downregulated, when the expression of SFRP5 was restored by demethylation agent DAC after it was methylated in breast cancer cell lines." (PMID 19586554, 2009). "For that reason, in the present study we initially evaluated the expression status of SFRP1, SFRP2 and SFRP5 in a panel of breast cancer cell lines." (PMID 18283316, 2008). "We have previously reported that expression of the Wnt antagonist genes SFRP1 and SFRP5 is frequently silenced by promoter hypermethylation in breast cancer." (PMID 18990230, 2008). "The antagonist role of SFRP5 in the canonical and non-canonical Wnt signalling path has been confirmed in breast cancer, where a higher level of SFRP5 mRNA was associated with a better prognosis." (PMID 37999144, 2023). "In breast cancer, several genes encoding inhibitors of canonical Wnt/β-catenin signalling have been reported to be frequently hypermethylated, for example, SFRP1, SFRP2, SFRP5, WIF1 and DKK1." (PMID 18826564, 2008). "In addition, we found that SFRP2 and SFRP5 are methylated in both cultured breast cancer cells and primary breast cancers at quite high frequencies." (PMID 18283316, 2008). "In contrast to an adverse prognostic value of SFRP1 or SFRP5 methylation in breast cancer, failure of SFRP2 methylation as a prognostic biomarker may be explained by redundant functions of these closely related SFRP molecules." (PMID 18990230, 2008). "Other downstream genes of miR-21-5p have also been reported in human diseases, such as SFRP5 in non‐alcoholic steatohepatitis, SMAD7 in lung cancer, PDCD4 in breast cancer, and LIFR in gastric cancer." (PMID 35549815, 2022). "Several Wnt/β-catenin antagonists were epigenetically repressed in breast cancer, including WIF1, SFRP1, SFRP2, SFRP5, DKK1, and DKK3." (PMID 28467796, 2017).
breast carcinoma (continued). "In the present study, seven potential breast cancer marker candidates (SFRP1, SFRP2, SFRP5, WIF1, DKK3, ITIH5, and RASSF1A) were studied with regard to early breast cancer detection in serum." (PMID 23320751, 2013). "We initially assessed promoter methylation of SFRP1, SFRP2, SFRP5, ITIH5, DKK3, and WIF1 in 112 paired breast cancer tissue and serum samples by using qualitative MSP." (PMID 23320751, 2013). "In human breast cancer, we have previously shown that the SFRP1 and SFRP5 promoter is epigenetically silenced in 61% and 73% of invasive breast carcinomas, respectively, each of which was associated with unfavorable patient prognosis." (PMID 18990230, 2008). "In breast cancer, SFRP1 and SFRP5 have been identified as targets of aberrant epigenetic inactivation to date, and either promoter methylation was found to be associated with unfavorable patient prognosis." (PMID 18990230, 2008).
ovarian carcinoma (16 papers, 2012 to 2024). A malignant neoplasm originating from the surface ovarian epithelium. "SFRP5, an independent risk factor for overall survival in patients with ovarian cancer, is hypermethylated alongside tumor growth and chemosensitivity in ovarian cancer." (PMID 31754130, 2019). "The results of the present study suggested that SFRP5 methylation may be associated with cell proliferation, colony formation and migration in ovarian cancer through Wnt/β-catenin signaling pathway." (PMID 31754130, 2019). "For instance, significant downregulation of the Wnt antagonist SFRP5 is observed through the promoter hypermethylation associated with overall survival in ovarian cancer; moreover, epigenetic silence of SFRP5 expression leads to activation of the Wnt pathway and promotes ovarian cancer progression." (PMID 29780815, 2018). "The aim of current study was to investigate the effects of single or combination treatment with curcumin and DAC on DNA methylation modification of SFRP5 and the Wnt/β-catenin signaling pathway in ovarian cancer." (PMID 31754130, 2019). "Epigenetic silencing of SFRP5 led to oncogenic activation of the Wnt pathway and contributed to ovarian cancer progression and carboplatin resistance through the transcription factor Twist-mediated EMT and AKT2 signaling." (PMID 35582723, 2019). "Hypermethylation of genes like ASS1, MLH1, and MSX1, and WNT pathway-related genes including DVL1, NFATC3, and SFRP5 was related to poor outcome of ovarian cancer patients treated with platinum-based chemotherapy." (PMID 28641578, 2017). "Promoter hypermethylation and silencing of a Wnt antagonist, secreted frizzled related protein 5 (SFRP5), was associated with ovarian cancer cell chemoresistance to cisplatin." (PMID 26828526, 2016). "A meta-analysis study showed that SFRP methylation may contribute to carcinogenesis especially in hepatocellular carcinoma and colorectal cancer cancers, in our previous study also showed that epigenetic silencing of SFRP5 may leads to ovarian cancer by oncogenic activation of the Wnt pathway." (PMID 31754130, 2019). "Accordingly, restoration of SFRP5 expression inhibits Wnt signaling and EMT thus sensitizing ovarian cancer cells to chemotherapy." (PMID 31614568, 2019). "Restored expression of SFRP5 reduces Wnt non-canonical signaling, promoting sensitivity to cisplatin in a mouse model of ovarian cancer." (PMID 32850327, 2020). "In our study, SFRP5 was fully methylated and genes silenced in SKOV3 ovarian cancer cells." (PMID 31754130, 2019). "SFRP1 SFRP2 and SFRP5 are methylated in ovarian cancer, and experimental overexpression or knockdown, demonstrated that epigenetic silencing of SFRP5 was related to tumour growth, invasion (via EMT) and chemosensitivity in ovarian cancer." (PMID 27196929, 2016). "In addition, SFRP5 expression inversely correlated with FOXM1 expression in ES-2 and TOV-21G ovarian cancer cells." (PMID 25537512, 2015). "The methylation frequencies of RASSFIA, CDH13, CACNA1A, HIN-1, DKN2B, sFRP5, ID4, and ESR were significantly higher in the clear-cell type of ovarian carcinoma than in the non-clear-cell type." (PMID 22871047, 2012). "Moreover, the methylation frequencies of RASSFIA, CDH13, CACNA1A, HIN-1, DKN2B, sFRP5, ID4, and ESR were significantly higher among OCCA than those in non-clear-cell types of ovarian carcinoma." (PMID 22871047, 2012).
coronary artery disease (15 papers, 2017 to 2025). "Meanwhile, SFRP5 exerts the restoring function in ischemic heart disease, as evidenced by SFRP5-deficient mice presenting more extensive inflammation, apoptosis, infarct size, and cardiac dysfunction consequent to ischemia/reperfusion injury." (PMID 34948320, 2021). "In Miyoshi's research, lower serum SFRP5 levels were significantly correlated with an increased risk of coronary artery disease." (PMID 32300333, 2020). "In two hospital-based studies serum SFRP5 was inversely associated with the metabolic syndrome and the severity of coronary artery disease." (PMID 28851362, 2017). "Moreover, it is crucial to explore the underlying mechanisms of SFRP5 in regulating the progression of coronary heart disease." (PMID 37957661, 2023). "SFRP5 is involved in the pathogenesis of coronary heart disease and has anti‐inflammatory, endothelial cell protection, anti‐fibrosis, and other effects." (PMID 40056066, 2025). "Plasma SFRP5 levels were significantly lower in patients with a history of heart failure (HF), coronary artery disease (CAD), and atrial fibrillation (AF; p = 0.001)." (PMID 37504530, 2023). "SFRP5 expression is decreased in coronary heart disease patients, and a high SFRP5 level indicates a good prognosis." (PMID 38188253, 2023). "The results highlighted that serum SFRP5 was decreased in unstable coronary artery disease patients as compared to stable coronary artery disease patients and control subjects." (PMID 33192583, 2020). "Recently, it has been investigated the relationship between serum level of SFRP5 and severity of coronary artery disease." (PMID 33192583, 2020). "Another study found that serum SFRP5 was lower in patients with coronary artery disease compared to controls and correlated inversely with the severity of the disease." (PMID 28851362, 2017). "However, lower concentrations of SFRP5 have been demonstrated in coronary artery disease (CAD) as well as higher levels of SFRP5 in chronic heart failure, measured by left ventricular end diastolic diameter (LVEDD) or levels of NT-proBNP." (PMID 36830849, 2023). "Moreover, serum SFRP5 levels were inversely related to the presence and complexity of coronary artery disease." (PMID 33192583, 2020). "SFRP5 levels of OSA patients were significantly lower than those of the non-snoring group, suggesting that lower SFRP5 may contribute to the risk of coronary artery disease in OSA patients." (PMID 32300333, 2020).
atherosclerosis (12 papers, 2020 to 2025). A disease characterized by the build-up of fatty material and calcium deposition in the arterial wall resulting in partial or complete occlusion of the arterial lumen. "Serum Secreted Curl Associated Protein 5 (SFRP5) is an anti‐inflammatory adipokine, which can reduce chronic inflammatory conditions by inhibiting the Wnt signaling pathway and has a regulatory effect on atherosclerosis and cardiovascular diseases." (PMID 40056066, 2025). "In addition, serum SFRP5 concentration was investigated for potential association with atherosclerosis in humans." (PMID 36984870, 2023). "SFRP5 weakens Wnt signaling by binding to Wnt5a, thereby inhibiting the development of cardiovascular diseases such as atherosclerosis, coronary heart disease, myocardial infarction, and myocardial hypertrophy." (PMID 35685732, 2022). "As a member of the SFRP family, SFRP5 plays a protective role in disease processes, such as atherosclerosis, and has metabolic relevance." (PMID 35685732, 2022). "sFRP5 acts as an anti-inflammatory mediator in atherosclerosis and works through the Wnt pathway." (PMID 35464772, 2022). "However, to date, human studies showing the relationships between SFRP5 and CHD are still scanty and direct roles of SFRP5 in the pathogenesis of atherosclerosis and myocardial infarction hitherto remain obscure." (PMID 32004418, 2020). "SFRP5 exerts anti-inflammatory effects through the suppression of the non-canonical WNT5/JNK signaling pathway, which can stimulate endothelial cell proliferation and vascular calcification associated with the pathogenesis of atherosclerosis." (PMID 32300333, 2020). "In vitro data suggest that Sfrp5 may play a protective role in the process of atherosclerosis." (PMID 34371968, 2021). "In spite of WNT5A has been particularly investigated in the progression of atherosclerosis, studies on the relationship between WNT5A and SFRP5 in cardiovascular diseases are limited." (PMID 33192583, 2020). "Moreover, the outcomes unveil a notable decrease in the SFRP5 concentration in high SYNTAX groups, suggesting that reduced levels of SFRP5 exert a detrimental effect on the pathology of atherosclerosis." (PMID 37957661, 2023).
metabolic syndrome (11 papers, 2017 to 2025). A cluster of metabolic risk factors for CARDIOVASCULAR DISEASES and TYPE 2 DIABETES MELLITUS. "Sfrp5 concentrations were lower in obese subjects, especially in those with metabolic syndrome." (PMID 34371968, 2021). "A recent hospital-based study found that circulating SFRP5 was associated with a lower odds of the metabolic syndrome irrespective of age, sex and risk factors for cardiometabolic diseases." (PMID 28851362, 2017). "Additionally, authors did not observe any significantly associations between SFRP5 concentration and biochemical parameters of metabolic syndrome as well as anthropometric measurements." (PMID 34184187, 2021). "Next, we evaluated the implication on SFRP5, WNT5A and PPARγ in SAT and VAT according to metabolic syndrome presence and their components (T2DM, dyslipidaemia and hypertension)." (PMID 36077270, 2022). "When metabolic syndrome parameters at initial assessment (glucose concentration, SBP, WC, TG, and HDL) were used in a standard forward stepwise regression model as independent variables, glucose concentration (b = 0.208, p < 0.05) was the best positive predictor for the change of Sfrp5 (ΔSfrp5)." (PMID 39339733, 2024). "When metabolic syndrome parameters at initial assessment (glucose concentration, SBP, WC, TG, and HDL) were used as independent variables in a standard forward stepwise regression model, SBP (b = 0.233, p < 0.05) was the best positive predictor of Sfrp5 concentrations." (PMID 39339733, 2024). "Conversely, Sfrp5 antagonizes Wnt signaling, particularly the non-canonical pathway, by binding to Wnt ligands, thereby reducing inflammation and oxidative stress in adipose and vascular tissues 59,60, which may protect against metabolic syndrome and CAD 61,62." (PMID 40303486, 2025).
Hepatic steatosis (10 papers, 2015 to 2024). Steatosis is a term used to denote lipid accumulation within hepatocytes. "Experimental evidence from murine disease models and studies on SFRP5 knockout mice suggests that secretion of SFRP5 by adipocytes prevents hepatic steatosis and metabolic dysfunction associated with liver fibrosis by modulating inflammatory cells within adipose tissue." (PMID 38872420, 2024). "Likewise, Sfrp5-deficient mice exhibited a greater degree of hepatic steatosis, with a higher triglyceride content when fed a high fat diet." (PMID 34371968, 2021). "In this sense, some studies have shown that SFRP5 can regulate metabolic disorders by improving hepatic lipid metabolism, inhibiting the growth of adipocytes, and alleviating hepatic steatosis." (PMID 34198988, 2021). "Experimental evidence indicates that Sfrp5 decreases accumulation of triglyceride and induction of hepatic steatosis through a pathway involving secreted lymphocyte antigen-6/urokinase-type plasminogen activator receptor-related peptide (Slurp-1)." (PMID 34371968, 2021). "Sfrp5 knockout mice fed a high fat diet developed adipose macrophage infiltration, severe glucose intolerance, and hepatic steatosis." (PMID 30704061, 2019). "It has previously been suggested that SFRP5 is a protective adipokine in hepatic steatosis, glucose intolerance and fibrosis." (PMID 29789397, 2018). "In a previous study, Sfrp5 knockout mice fed high fat diet developed adipose macrophage infiltration, severe glucose intolerance and hepatic steatosis." (PMID 28824700, 2017). "Notably, SFRP5 administration reversed hyperglycaemia and hepatic steatosis in multiple mouse models of metabolic dysfunction." (PMID 38872420, 2024). "For example, mice deficient in Sfrp1 exhibit increased adiposity and hepatic steatosis, and SFRP5 signaling has been shown to suppress non-alcoholic steatohepatitis." (PMID 38137817, 2023). "SFRP5 administration in diabetic and obese mice leads to decreased glucose intolerance, brought about by high-caloric intake and characterized by macrophage infiltration and hepatic steatosis in adipose tissues." (PMID 29789397, 2018). "On the one hand, we observed a positive correlation between SFRP5 mRNA in SAT and proinflammatory cytokines, such as IL-8 and IL-17, which presented high levels in patients with fatty liver disease, consistent with our results." (PMID 36077270, 2022). "Serum Sfrp5 did not correlate with markers for the severity of NAFLD like hepatic steatosis index and liver enzymes." (PMID 34371968, 2021). "Interestingly, some genes that have been described to suppress the high body fat phenotype, hepatic steatosis, and potentially also myosteatosis are strongly downregulated in tumors because they are putative tumor-suppressor genes, such as SFRP1, SFRP5, and DKK3." (PMID 38137817, 2023).